RN7SKP195 (RN7SK pseudogene 195)
Gene: Miscellaneous RNA gene on chromosome 1 (237,120,807 to 237,121,109, forward strand). Ensembl gene ENSG00000252396.
Homologues: Orthologues: chimpanzee 7SK (89% identical), guinea pig 7SK (48% identical), mouse Gm55664 (44% identical), mouse Gm54997 (43% identical), mouse Gm54777 (9% identical). Paralogues in human: 7SK (55% identical), RN7SKP133 (55% identical), RN7SKP48 (55% identical), RN7SKP124 (54% identical), RN7SKP71 (54% identical), RN7SKP85 (54% identical), RN7SKP180 (53% identical), RN7SKP3 (53% identical), RN7SKP203 (53% identical), RN7SKP286 (53% identical), RN7SKP291 (53% identical), RN7SKP176 (53% identical), and 283 more.